S100P (S100 calcium binding protein P)
Diseases named in the same sentence as S100P in open-access papers (continued):
Sharing a sentence is not in itself a finding about the gene and the disease.
liver cancer (4 papers, 2009 to 2023). An epithelial or non-epithelial malignant neoplasm that arises from the liver. "Our results indicated that S100P was up-regulated in HCC, suggesting a possible role of S100P may play in liver cancer." (PMID 19171046, 2009). "Liver cancer cell lines express higher S100P levels than normal non-malignant hepatocytes, which frequently lack S100P." (PMID 23166536, 2012).
non-small cell lung carcinoma (4 papers, 2009 to 2021). A group of at least three distinct histological types of lung cancer, including non-small cell squamous cell carcinoma, adenocarcinoma, and large cell carcinoma. "A recent paper investigating PORCN in Non Small Cell Lung Carcinoma illustrated that loss of PORCN downregulates S100P at the mRNA and protein levels in a β-catenin independent manner, similar to what we have shown for APEH." (PMID 22509316, 2012). "Additionally, RAB25 may be linked to tumor aggressiveness and metastasis, and S100P may be a diagnostic marker of non-small-cell lung cancer." (PMID 20142997, 2010).
oral cancer (4 papers, 2013 to 2022). "The concentration of S100P mRNA was three times higher in the oral cancer group than in the healthy group." (PMID 35186787, 2022). "The results indicated a threefold increase of S100P in oral cancer patients as compared to healthy subjects." (PMID 34093888, 2021).
triple-negative breast carcinoma (4 papers, 2016 to 2025). An invasive breast carcinoma which is negative for expression of estrogen receptor (ER), progesterone receptor (PR), and human epidermal growth factor receptor 2 (HER2). "S100P, widely known for its pro-cancer role across multiple cancer types, has also shown clinical relevance in triple negative breast cancer as its higher expression correlates with recurrence related events and higher metastasis in a cohort of 98 patients." (PMID 40420099, 2025). "S100P is highly expressed in many cancer tissues, including triple negative breast cancer, and it is related to adverse clinical outcomes such as lymphatic metastasis and tumor growth." (PMID 36263421, 2022). "Furthermore, OS of patients with S100P mRNA abundance was significantly lower in luminal B, grade I or triple-negative breast cancer." (PMID 28051137, 2017).
gallbladder cancer (3 papers, 2021 to 2024). "Elevated S100P expression has been found in several other cancers, including colorectal, lung, where it correlates with the activity of the oncogenic PI3K/AKT signaling pathway, and gall bladder cancers." (PMID 36985425, 2023).
gastric tumors (3 papers, 2008 to 2024). "They found that S100P protein expression was highly elevated in all tumor tissues, with the most prominent expression observed in gastric tumors." (PMID 39284282, 2024). "Consistent with our findings, S100P is also identified to be a predictor of stomach tumor, and is essential for tumor aggressiveness in various types of cancer." (PMID 36455876, 2022). "Immunostaining of tumor specimens showed that S100P protein is expressed in all the tumor categories included in the study, being most prevalent in gastric tumors." (PMID 18282279, 2008).
glioblastoma (3 papers, 2014 to 2023). The most malignant astrocytic tumor (WHO grade IV). "We found that suppressing S100P expression in glioblastoma cells inhibited anchorage independent growth when compared to uninfected and shGFP cells." (PMID 24821384, 2014). "Our study revealed that blocking S100P expression inhibited glioblastoma cell migration and invasion." (PMID 24821384, 2014). "We also extended the current study to examine the effect of DEHP treatment on glioblastoma cells in the presence and absence S100P expression." (PMID 24821384, 2014). "To determine the role of S100P on anchorage independent growth in glioblastoma cells, we examined colony formation after blocking the expression of S100P." (PMID 24821384, 2014). "Moreover it has been described that bis(2-ethylhexyl)phthalate (DEHP) modulates cell migration, invasion and anchorage independent growth through targeting S100P in LN-229 glioblastoma cells." (PMID 30645699, 2019). "In turn, the functional role of family S100P proteins, which is associated with drug resistance and metastasis in many malignancies, has not been fully documented in glioblastoma." (PMID 30645699, 2019). "Furthermore, we analyzed the effects of suppressing S100P expression on migration and invasion of LN-229 glioblastoma cells." (PMID 24821384, 2014). "In this study, we hypothesized that DEHP modulates cell migration, invasion and anchorage independent growth through targeting S100P in LN-229 glioblastoma cells." (PMID 24821384, 2014). "The expression of S100P in glioblastoma cell lines was knocked down using shS100P." (PMID 24821384, 2014). "This study is the first to demonstrate the effects of DEHP on glioblastoma cells, and implicates S100P as a potential therapeutic target that may be useful as a drug response biomarker." (PMID 24821384, 2014). "Furthermore, our study revealed that silencing S100P using lentiviral mediated RNAi significantly inhibited glioblastoma cell growth and invasion." (PMID 24821384, 2014). "In this study, we examined whether DEHP-induced cell transformation in glioblastoma is mediated through S100P." (PMID 24821384, 2014). "Consequently, we suppressed S100P expression in glioblastoma cancer cells using lentiviral knockdown to investigate its role in glioblastoma." (PMID 24821384, 2014). "Our results indicate that S100P may contribute to the invasive nature of glioblastoma." (PMID 24821384, 2014). "Thus, interference with S100P may provide a novel approach for development of treatment of glioblastoma." (PMID 24821384, 2014). "Silencing S100P and DEHP treatment inhibited LN-229 glioblastoma cell proliferation and induced apoptosis." (PMID 24821384, 2014). "We observed similar patterns and levels of inhibition in 3 other glioblastoma cell lines (data not shown) suggesting that S100P plays a major role in proliferation of glioblastoma cells." (PMID 24821384, 2014). "In this study, we examined the role of S100P mediating the effects of the environmental contaminant, DEHP, in glioblastoma cells (LN-229) by assessing cell proliferation, apoptosis, anchorage independent growth, cell migration and invasion following DEHP exposure." (PMID 24821384, 2014). "The role of S100P in glioblastoma progression has not yet been investigated." (PMID 24821384, 2014). "The functional role of S100P in glioblastoma has not been fully investigated." (PMID 24821384, 2014). "However, the functional role of S100P in glioblastoma has not been elucidated." (PMID 24821384, 2014).
glioma (3 papers, 2022 to 2023). A benign or malignant brain and spinal cord tumor that arises from glial cells (astrocytes, oligodendrocytes, ependymal cells). "However, there have been few studies on S100P in glioma and the functional role of S100P and mechanisms in glioma has not been clearly elucidated until now." (PMID 36046652, 2022).
invasive ductal carcinomas (3 papers, 2016 to 2024). "Through bioinformatic analysis, it was observed that the S100P expression was increased in invasive ductal carcinomas when compared with the adjacent normal tissues." (PMID 39594999, 2024). "S100P is a 95-amino-acid protein, whose expression is positively correlated with the progression of PanIN, indicating that S100P is essential to the progression from PanIN to invasive ductal adenocarcinoma." (PMID 37304241, 2023). "Using a monoclonal antibody against the same amino acid sequence of the cloned gene, the S100P protein was then localized by immunohistochemistry in ductal hyperplasia, in situ, and invasive ductal carcinoma, but not in the normal tissues." (PMID 39594999, 2024).
lymph node metastasis (3 papers, 2020 to 2022). "S100P-SPP1 + iCCApps had less lymph node metastasis, larger tumor volume, and better prognosis than S100P + SPP1− iCCAphl." (PMID 35347134, 2022). "Fortunately, S100P may be an effective target for inhibiting lymph node metastasis because these CCIDs in PC are partially regulated by S100P." (PMID 34527585, 2021).
periodontitis (3 papers, 2011 to 2025). An acute or chronic inflammatory process that affects the tissues that surround and support the teeth. "However, carbonic anhydrase 1 and protein S100-P, they were overexpressed in periodontitis (fold-change around 4.3 for both), as in previous studies; however, their relationship with periodontitis is still unclear." (PMID 40384977, 2025). "Although cornifin-A and S100-P were identified by small peptide hits, S100-P was upregulated and cornifin-A was downregulated in the GCF of periodontitis patients compared to healthy individuals, in both our study and the previous study." (PMID 21794177, 2011). "Moreover, S100-P and S100-A6 were also found to be upregulated, as in previous studies, although their possible relationship with periodontitis has not yet been discovered." (PMID 40384977, 2025).
rectal carcinoma (3 papers, 2016 to 2023). A malignant epithelial neoplasm that arises from the rectum and invades through the muscularis mucosa into the submucosa. "Interestingly, expression of S100P protein was associated with the localisation of the primary CRC tumour: the rate of S100P expression increased from the right to the left, being the highest in the rectal carcinomas." (PMID 26880885, 2016). "Notably, the S100P protein expression was related to the localization of the primary CRC tumor: the levels of S100P expression were elevated from the right to the left, being the maximum in the rectal carcinomas." (PMID 33117687, 2020).
type 2 diabetes (3 papers, 2021 to 2025). "S100P serum levels have been proposed as an indicator of peripheral neuropathy in type 2 diabetes." (PMID 41373473, 2025). "Serum S100P levels are elevated in patients with diabetic peripheral neuropathy and are considered a significant indicator of peripheral neuropathy in patients with type 2 diabetes." (PMID 36187124, 2022).
Allergy (2 papers, 2009 to 2020). An allergy is an immune response or reaction to substances that are usually not harmful. "Direct inhibition of S100P function has been achieved by use of a monoclonal antibody and with the anti-allergy drug cromolyn 1, indicating the possibility for the development of small molecules to directly target S100P." (PMID 32707527, 2020). "The anti-allergy drug cromolyn binds S100P and will block S100P-RAGE interaction." (PMID 19292913, 2009).
bladder adenocarcinoma (2 papers, 2014 to 2025). "S100P along with GATA3 and napsin A expression help to distinguish lung-derived bladder adenocarcinoma from primary bladder adenocarcinoma." (PMID 41164170, 2025).
colorectal adenoma (2 papers, 2021 to 2022). An adenoma that arises from the colon or rectum. "Several studies showed that the S100P expression is upregulated in colorectal adenomas or carcinomas compared to mucosa tissue." (PMID 35597866, 2022). "Upregulation of S100P was described in colorectal adenoma compared to normal tissue." (PMID 33466593, 2021).
esophageal cancer (2 papers, 2013 to 2018). A primary or metastatic malignant neoplasm involving the esophagus. "S100P, on the other hand, could be targeted via RAGE protein which would serve as an inhibitor to S100P’s contribution to esophageal cancer’s overall progression." (PMID 29868478, 2018).
invasive breast carcinoma (2 papers, 2023 to 2024). A carcinoma that infiltrates the breast parenchyma. "In this study, both MEK2 and S100P were upregulated in blood and tumor samples of invasive breast cancer." (PMID 37445737, 2023). "FGF2 and S100P were overexpressed (p < 0.05) in both DCIS and invasive breast cancer patient blood samples." (PMID 37445737, 2023).
leukemia (2 papers, 2017 to 2021). A malignant (clonal) hematologic disorder, involving hematopoietic stem cells and characterized by the presence of primitive or atypical myeloid or lymphoid cells in the bone marrow and the blood. "For instance, a role of S100P has been reported in leukemia, while the exact function of S100P in leukemia and the signal pathways involved in this process are not completely understood." (PMID 29379499, 2017).
leukoplakia (2 papers, 2021 to 2022). A white patch or plaque on a mucous membrane that cannot be characterized clinically or pathologically as any other disease. "Three proteins—CD44, S100A7, and S100P—were significantly different in dysplastic leukoplakia compared to the normal cohort, with CD44 showing the highest sensitivity." (PMID 34830890, 2021).
metastatic disease (2 papers, 2011 to 2024). "The IHC results showed that the expression level of S100P was higher in most metastatic tumors than that in the matched primary tumors." (PMID 38342601, 2024).
nasopharyngeal carcinoma (2 papers, 2020). A carcinoma arising from the nasopharyngeal epithelium. "S100P is related to the proliferation and migration of nasopharyngeal carcinoma cells." (PMID 32819300, 2020). "Moreover, MMP9 expression was increased in pancreatic carcinoma (BxPC3) and nasopharyngeal carcinoma (C666-1) along with MMP2 that was triggered by S100P." (PMID 32443845, 2020).
Sepsis (2 papers, 2019 to 2022). Sepsis is defined as life-threatening organ dysfunction caused by a dysregulated host response to infection. "The results showed that all of the genes showed favorable diagnostic potential for both trauma and sepsis, and specifically, high level of S100P was associated with poor 28-day survival of sepsis patients." (PMID 35615364, 2022). "Notably, we identified a list of 14 immune-related genes concurrently dysregulated in trauma and sepsis showing favorable diagnostic value, among which S100P can predict prognosis of sepsis patients." (PMID 35615364, 2022). "The results showed that S100P expression could stratify survival differences between the two groups (log-rank P = 0.019), suggesting S100P as a potential prognostic biomarker for sepsis." (PMID 35615364, 2022). "S100P is produced mainly by the central nervous system, and the elevated expression level of S100P in sepsis was found by other groups, but its role as a prognostic biomarker for sepsis has not been previously reported." (PMID 35615364, 2022).
acne (1 paper, 2018). An inflammatory process of the sebaceous glands which is characterized by comedones, nodules, papules and/or pustules on the skin. "Compared with normal skin, S100P and FDXR expression were significantly higher but K10 expression was slightly lower in acne lesion." (PMID 29850553, 2018). "In addition, immunostaining demonstrated overexpression of S100P and FDXR but mild downexpression of K10 in acne lesion, while ADA expression was absent in both acne lesion and normal skin." (PMID 29850553, 2018).
adenosquamous carcinoma (1 paper, 2020). A carcinoma composed of malignant glandular cells and malignant squamous cells. "In our study, the expression of S100P in adenosquamous carcinoma-derived RL95–2 cells was much higher than that in adenocarcinoma-derived Ishikawa cells, which supported Jiang’s opinion that S100P is overexpressed in endometrial adenosquamous carcinomas." (PMID 32883230, 2020).
ankylosing spondylitis (1 paper, 2015). An autoimmune chronic inflammatory disorder characterized by inflammation in the vertebral joints of the spine and sacroiliac joints. "However, neither GNG11 nor S100P have been reported to be associated with ankylosing spondylitis yet." (PMID 25688367, 2015).
asthma (1 paper, 2016). "qPCR confirmed that S100P, S100A16, MAL and MUC1 were significantly increased in the asthma group post-meal." (PMID 26751474, 2016). "In this study, we found that the expression of S100P and S100A16 genes were significantly increased in the asthma group at 4 h post-meal compared with baseline." (PMID 26751474, 2016). "Confirming the microarray analysis, we determined that S100P, S100A16, MAL and MUC1 were significantly increased in the asthma group at 4 h post-meal compared with baseline." (PMID 26751474, 2016).
autoimmune pancreatitis (1 paper, 2022). "Another study utilized IMP3, Maspin, S100P, and von-Hippel-Lindau gene protein (pVHL) for comparison between autoimmune pancreatitis (AIP), PDAC, and normal pancreas specimens." (PMID 35565450, 2022).
basal cell neoplasm (1 paper, 2013). A neoplastic proliferation of basal cells in the epidermis (part of the skin) or other anatomic sites (most frequently the salivary glands). "β-catenin, CK5/6, CD117, and S100P protein were helpful for differentiating basal cell neoplasms from ACC." (PMID 24143938, 2013).
bladder tumours (1 paper, 2020). "The results from this study nonetheless provides new information with regards to S100P staining in bladder tumour cells as well as its association with cancer grade, stage and recurrence following treatment via TURBT." (PMID 33238953, 2020). "There was significantly increased expression of CD31 (p < 0.001), HER-2 (p = 0.032), S100P (p < 0.001), COX-2 (p < 0.001), VEGFR-3 (p < 0.001) and decreased expression of thrombomodulin (p = 0.010) and CEACAM-1 (p < 0.001) in bladder tumours compared to normal bladder tissues." (PMID 33238953, 2020).
bladder urothelial carcinoma (1 paper, 2021). "Classification of a carcinoma of either bladder urothelial carcinoma or prostate adenocarcinoma reaches 100% accuracy by a combination of gene expressions of uroplakin II, S100P, NKX3.1, and PSA." (PMID 33762601, 2021). "Combination of NKX3.1, PSA, uroplakin II and S100P is therefore proposed to be the favored immunohistochemical test to resolve the dilemma of distinguishing between bladder urothelial carcinomas and prostate adenocarcinoma." (PMID 33762601, 2021). "In descending order of importance for the urothelial lineage gene expressions, UKP2, S100P, GATA3 and THBD were the most important predictors for bladder urothelial carcinoma based on the discriminant loading > 0.3." (PMID 33762601, 2021).
choledocholithiasis (1 paper, 2022). Presence or formation of gallstones in the common bile duct. "Another study showed that S100P levels in bile were significantly elevated in patients with CCA, and bile S100P could distinguish between patients with CCA and choledocholithiasis with sensitivity and specificity of 92.9% and 70.0%, respectively." (PMID 36389727, 2022).
choriocarcinoma (1 paper, 2023). An aggressive malignant tumor arising from trophoblastic cells. "High levels of S100P have been linked to increased cell viability and cellular proliferation in JAR cells, but not other choriocarcinoma cell lines (Jeg-3 or BeWo) or in extravillous trophoblast (HTR8/SVneo)." (PMID 37627296, 2023).
chronic cholecystitis (1 paper, 2024). "One study demonstrated negative S100P staining in NL gallbladder tissue and positive staining in 50% of chronic cholecystitis cases." (PMID 39334193, 2024).
chronic hepatitis (1 paper, 2022). An active inflammatory process affecting the liver for more than six months. "Our results revealed that there were significantly higher percentages of HBsAg positive status, chronic hepatitis, and liver cirrhosis in S100P-SPP1 + iCCApps than in S100P + SPP1− iCCAphl, further highlighting their distinct pathogenic background." (PMID 35347134, 2022).
Cirrhosis (1 paper, 2025). A chronic disorder of the liver in which liver tissue becomes scarred and is partially replaced by regenerative nodules and fibrotic tissue resulting in loss of liver function. "Finally, prospective multicenter trials should evaluate liquid biopsy applications, particularly for the 14-gene HBV signature (ABCA8, S100P) and 164 cirrhosis-to-HCC transition markers, benchmarked against current standards like AFP." (PMID 40678800, 2025).